CX3CR1 (C-X3-C motif chemokine receptor 1)
Diseases named in the same sentence as CX3CR1 in open-access papers (continued):
Sharing a sentence is not in itself a finding about the gene and the disease.
Stroke (continued). "As stroke pathology progresses into the acute phase (24 h–7 d), the CX3CR1/CX3CL1 axis undergoes critical spatiotemporal reprogramming." (PMID 40722349, 2025). "It is now well established that the CX3CR1 signaling axis plays a stage-dependent dual role following stroke." (PMID 40722349, 2025). "By integrating advances across neuroimmunology and systems biology, this work establishes a temporally sequenced targeting strategy for CX3CR1 modulation, providing a foundational framework for next-generation precision stroke therapeutics." (PMID 40722349, 2025). "These systematic endeavors will establish the scientific foundation for implementing the CX3CR1-based triple precision strategy in stroke patients." (PMID 40722349, 2025). "This review delineates the core pathophysiological signature of stroke-induced CX3CR1/CX3CL1 signaling: its spatiotemporally evolving dual neurotoxic/neuroreparative effects." (PMID 40722349, 2025). "The core scientific challenges surrounding CX3CR1 constitute critical bottlenecks impeding the clinical translation of stroke precision therapeutics." (PMID 40722349, 2025). "In summary, the CX3CR1/CX3CL1 signaling axis serves as the central regulatory mechanism for post-stroke brain repair." (PMID 40722349, 2025). "In stroke management, precise pathological staging is fundamental for targeted CX3CR1/CX3CL1 modulation and essential for elucidating disease mechanisms, optimizing therapies, and predicting outcomes." (PMID 40722349, 2025). "Chronic-phase CX3CR1 signaling dysfunction correlates directly with long-term neurocognitive outcomes in stroke survivors." (PMID 40722349, 2025). "Our observation revealed that, as compared with CX3CR1+/− mice, CX3CR1−/− mice had significantly inhibited microglial phagocytic activation and morphological alterations after stroke." (PMID 38421089, 2024). "We report here that post-stroke Cx3cr1-CreER+/−;Nhe1flox/flox (Nhe1 cKO) brains displayed stimulation of microglial transcriptomes of rate-limiting enzyme genes for glycolysis, tricarboxylic acid cycle, and oxidative phosphorylation." (PMID 35017668, 2022). "In models of stroke, epilepsy, and amyotrophic lateral sclerosis, a decrease of CX3CR1 or a rise of its ligand seem to be protective." (PMID 36092814, 2022). "In this study, laminin was increased 7 days after the occlusion in all the stroke groups (wildtype, and in CX3CR1 and in CCR2 knockouts)." (PMID 35743229, 2022). "We also injected the virus into Cx3cr1-Cre*Ai6 mice, 18 days after the virus injection, mice were operated with sham or stroke." (PMID 34094642, 2021). "Together, these experiments support the idea that cx3cr1 deletion contributes in the regulation of GABAA receptor subunits synthesis in the recovery phase of stroke." (PMID 34417725, 2021). "On the other hand, the CX3CR1−/− (CX3CR1 loss of function) mouse model resulted in a reduction in BBB breakdown and a decrease in the area of stroke injury." (PMID 34276530, 2021). "Consistent with cultured microglia in vitro, CX3CR1 expression in MCAO stroke mouse was increased 30% as compared to non-stroke sham-surgical mice." (PMID 32676009, 2020). "PTX–treated stroke mice decreased the CX3CR1 expression back to a level similar to sham-surgical mice." (PMID 32676009, 2020). "The reduction in stroke-induced CX3CR1 protein levels in VPS35 cKO brain suggests a role of microglial VPS35 in stabilizing CX3CR1 proteins in response to stroke." (PMID 31771656, 2019). "Further investigations are necessary to test the view if CX3CR1 acts as a cargo of VPS35 in microglial cells to participate in stroke-induced injury response." (PMID 31771656, 2019). "In a focal ischemic model, it has been reported that many CCR2+ Mo/MΦ that had invaded after the stroke later transdifferentiated to CX3CR1+ Mo/MΦ20." (PMID 29844029, 2018). "Targeting CX3CR1 in order to inhibit apoptosis limits cell death after ischemia, offering a unique approach for stroke therapy." (PMID 29323156, 2018).
Stroke (continued). "In view of the dispersed data related to CX3CL1/CX3CR1 and ischemic stroke it is difficult to judge the neuroprotective role of CX3CL1/CX3CR1 signaling and the future possibility to manipulate this pathway pharmaceutically to reduce the sequel of stroke." (PMID 30319362, 2018). "The chemokine fractalkine (CX3CL1) and its receptor CX3CR1 play a fundamental role in the pathophysiology of stroke." (PMID 29323156, 2018). "In the meantime, other study has demonstrated that CX3CR1 can mediate neuronal apoptosis in a cerebral ischemic model, thus potentially playing a role in the pathophysiology of stroke." (PMID 30123110, 2018). "Based on previous studies, we hypothesized that CX3CR1 deficiency may contribute to the morpholgy of microglia in the proximal peri-infarct area during the first 2 weeks with possible consequences for their function and contribution to recovery of lost neurological function after stroke." (PMID 28061814, 2017). "Both bone marrow-derived macrophages (CCR2+) and microglia (CX3CR1+) increased in the peri-infarct regions of mice subjected to bone fracture before pMCAO compared to stroke-only mice." (PMID 27089041, 2016). "Our study supports the idea that downregulation of the FKN/CX3CR1 pathway diminishes detrimental actions of post-stroke inflammation." (PMID 25881123, 2015). "CX3CR1-positive cells can be detected in the ischemic tissue from 24 hours and are strongly upregulated with a peak at day 7 after stroke." (PMID 25881123, 2015). "Acutely after stroke there are more brain resident CX3CR1+ microglial cells present in the ischemic territory that are responsive to FKN." (PMID 25881123, 2015). "Microglia activation plays an important role in the pathological progression after stroke, and is regulated by CX3CR1." (PMID 24490760, 2014). "Collectively, these data identify CX3CR1 as a putative therapeutic target for selectively reducing neurodestructive inflammatory cascades after stroke." (PMID 24490760, 2014). "Transcripts of chemokine receptors were also increased in the ischemic hemisphere of wildtype control mice, with a peak at 12 h for CCR1 and a peak at 7 d for CCR2, CCR5 and CX3CR1 after stroke." (PMID 23301011, 2013). "DNTs might influence microglia’s activation state through CX3CR1; thus, they inhibit the M2 state ex vivo, which might contribute to cerebral inflammation post-stroke." (PMID 41373643, 2025). "DNTs might influence microglia through CX3CR1 and inhibit an M2 state ex vivo, which might contribute to cerebral inflammation post stroke." (PMID 41373643, 2025). "Temporally targeting CX3CR1 signaling may offer a key basis for developing next-generation precision neural repair strategies for stroke." (PMID 40722349, 2025). "Our study showed that CX3CR1 gene deletion inhibited GSDMD protein activation after stroke." (PMID 38421089, 2024). "However, research with CX3CR1−/− mice mainly focused on inhibiting microglial neurotoxicity and maintaining an early protective microenvironment after stroke." (PMID 38421089, 2024). "CX3CR1 gene deletion could significantly suppress microglia pyroptosis and then improve cognitive dysfunction after stroke." (PMID 38421089, 2024). "According to recent reports, when inhibition of CX3CR1 is targeted early, or CX3CL1 expression levels are increased, administration of exogenous CX3CL1 after ischemia can reverse the neurological damage caused by stroke to some extent." (PMID 34276530, 2021). "Several studies have focused on the involvement of the CX3CL1/CX3CR1 pathway in stroke pathophysiology, presenting ambiguous conclusions on whether activation of the chemokine cascade possesses a neuroprotective or detrimental role." (PMID 34417725, 2021). "However, both detrimental and beneficial effects have been attributed to CX3CR1/CX3CL1 signaling in stroke." (PMID 33058417, 2020). "Such stroke-induced CX3CR1 protein levels were abolished in VPS35CX3CR1 mice." (PMID 31771656, 2019).
Stroke (continued). "However, upon stroke injury, CX3CR1 levels were increased in injury side of cortex and hippocampus in control mice." (PMID 31771656, 2019). "We will discuss the relevance of CX3CR1 activation for immune cell activation after stroke." (PMID 28061814, 2017). "We hypothesized that microglia morphology indicative for their activation status is affected by the presence of CX3CR1 beyond the time window of neuroprotection after stroke." (PMID 28061814, 2017). "Moreover, we will elaborate on the consequences of CX3CR1 knockout on different results obtained in previous studies in regard to functional outcome and lesion size after experimental stroke." (PMID 28061814, 2017). "We also demonstrate that CX3CR1 deficiency has no beneficial effect on lesion size neither it affects early functional outcome after stroke." (PMID 28061814, 2017). "Mice that received bone fracture 6 hours before pMCAO also had more microglia (39.6±3.66%, CX3CR1+) in the peri-infarct regions compared to stroke-only mice (24.2±4.88%, p <0.001) and mice that received bone fracture 24 hours before pMCAO (31.4±5.54%, p = 0.01)." (PMID 27089041, 2016). "Indeed, TNFα, IL-1α, IL-1β, CCL2, CCL3 and CX3CR1 transcript expression differed in the ischemic cerebral tissue of TREM2-KO mice compared to littermate controls at day 7 after stroke." (PMID 23301011, 2013). "Therefore, reducing primary brain injury by CX3CR1 gene deletion to inhibit neuroinflammation early after stroke could improve cognitive function at later time points." (PMID 38421089, 2024). "In addition, the CX3CL1/CX3CR1 chemokine pathway is involved in stroke pathology." (PMID 34417725, 2021). "Interestingly, we find prevention of exacerbation of ischemic lesion was accompanied with reduced cleaved Caspase 3 positive neurons in the peri-infarct area at 72 hours after initial stroke in CX3CR1-/- mice compared to WT mice, inconsistent with a previous report." (PMID 24490760, 2014). "As previously stated, the CX3CR1 and TREM2 pathways exhibit precise synergistic regulation that jointly controls acute neuroinflammatory dynamics after stroke." (PMID 40722349, 2025). "Our study also showed that CX3CR1 gene deletion inhibited the expression of NLRP3, ASC, caspase‐1, IL‐1β, IL‐18, and NF‐κB p65 protein after stroke." (PMID 38421089, 2024). "In order to better reveal the neuroprotective effects of boosting microglial Igf1 expression on stroke outcomes, AAV‐DIO‐siTrem2 combined with AAV‐DIO‐Igf1 were simultaneously injected into Cx3cr1‐Cre+ mice brains prior to MCAO." (PMID 38151703, 2024). "In addition, CX3CR1−/− mice could reverse infarct volume in the hippocampus region post‐stroke." (PMID 38421089, 2024). "Following an acute injury such as stroke, the apoptotic neurons release a chemotactic signal such as fractalkine/CX3CL1 and microglia expressing the fractalkine receptor (CX3CR1), which promotes phagocytosis of apoptotic cells expressing CX3CL1." (PMID 31814819, 2019). "The CX3CR1/CX3CL1 axis exhibits phase-dependent functional duality, with its cellular sources, signaling intensity, and biological consequences evolving across stroke progression, exhibiting both neuroprotective and neurotoxic manifestations at different stages." (PMID 40722349, 2025). "To further confirm that CX3CR1 gene deletion could inhibit ischemic injury‐induced neuroinflammation, we employed [18F]‐DPA‐714 PET imaging to monitor the mouse brain after stroke." (PMID 38421089, 2024). "However, at 14 and 28 days after stroke, CCR2+ cells are mainly found in the lesion core, which is surrounded by CX3CR1+ monocytes/macrophages as shown by the transfer of CX3CR1GFP/+CCR2RFP/+ bone marrow into wild‐type mice." (PMID 33058417, 2020). "To further analyze the phenotype of CX3CR1+ green fluorescent cells in CX3CR1GFP/+ mice, we performed immunohistochemistry in the animals that had been sacrificed after 2PLSM-experiments at d14 after stroke." (PMID 25881123, 2015).
Stroke (continued). "We could show that the findings regarding the role of DNTs from murine stroke models coincided with findings using human cells: While HLA-DR did not change after coculture with DNTs, the percentage of CX3CR1 decreased significantly." (PMID 41373643, 2025). "However, CX3CR1 gene deletion could influence microglia pyroptosis and AHN in the early phase of stroke and then improve cognitive dysfunction in the chronic phase." (PMID 38421089, 2024). "Additionally, the CX3CR1-dependent neural repair window identified in rodent models may not directly translate to human stroke patients due to longer disease courses with greater pathophysiological complexity." (PMID 40722349, 2025). "In addition to the reduced infarct area in response to the ischemic injury, both VPS35 and CX3CR1 mutant mice show increased anti-inflammatory, but not pro-inflammatory, microglial activation by stroke and reduced stroke-induced expressions of pro-inflammatory cytokines." (PMID 31771656, 2019). "However, it should be noted that minocycline is not microglia-specific and genetic deletion of Cx3Cr1 only alters rather than completely abolishes microglial behavior; therefore, these and other observational data could not unequivocally conclude that microglia cause BBB disruption after stroke." (PMID 39110702, 2024). "The reduced CX3CR1-driven GFP in (b) region of the control, but not mutant, peri­infarct area led us to ask whether stroke-induced stage 1 DAM might be impaired in VPS35CX3CR1 mice." (PMID 31771656, 2019).
Sepsis (40 papers, 2011 to 2026). Sepsis is defined as life-threatening organ dysfunction caused by a dysregulated host response to infection. "On the other hand, CX3CR1 is also involved in the pathogenesis of sepsis in human, and a study on polymorphisms in the CX3CR1 gene showed that the I249 CX3CR1 allele correlated with more monocyte adhesion and less renal damage." (PMID 40508161, 2025). "Consistent with our findings, previous studies have shown that reduced CX3CR1 expression on circulating monocytes is a hallmark of sepsis-induced immunosuppression." (PMID 40761792, 2025). "For sepsis, CX3CR1, PID1 and PTGDS are strongly associated with immune pathways such as “Allograft rejection” and “Asthma”." (PMID 39763654, 2024). "A predictive model for sepsis was created using three crucial genes—CX3CR1, PID1, and PTGDS—to enhance diagnostic precision." (PMID 39763654, 2024). "A clinical study involving 291 patients further indicated the potential of CX3CR1 as an early diagnostic biomarker for infections and sepsis in emergency settings." (PMID 38263335, 2024). "Our survival analysis suggests that elevated expression of CX3CR1 is associated with better prognosis in sepsis and ARDS." (PMID 39763654, 2024). "This array of findings aligns with the observed reduced expression of CX3CR1 in our cohorts of both sepsis patients and those at high risk for the condition, in contrast to their respective control groups." (PMID 38263335, 2024). "A previous study demonstrated that the internalization of CX3CR1 is closely associated with immunoparalysis in the late phase of sepsis." (PMID 36860871, 2023). "Downregulation of Cx3cr1 expression has previously been linked to sepsis in patients, and exposure to Escherichia coli, S. aureus, or purified LPS can lead to decreased expression by monocytes ex vivo." (PMID 36054235, 2022). "This loss of monocyte-specific CX3CR1, which causes sepsis-induced lethality in humans, compromised this cell’s ability to respond to a fractalkine challenge." (PMID 30253780, 2018). "We observed that decreased CX3CR1 mRNA expression is a very early phenomenon in critically ill patients and is associated with mortality independently of the presence of shock or sepsis." (PMID 27364780, 2016). "However, although CX3CR1 showed excellent diagnostic performance, its clinical application as a biomarker needs further validation to confirm its utility in sepsis diagnosis and prognosis." (PMID 41332909, 2025). "Current research suggests that decreased CX3CR1 expression on circulating monocytes may represent a novel feature of immunosuppression caused by sepsis." (PMID 38245687, 2024). "Moreover, low CX3CR1 is associated with marked neuronal loss after systemic inflammation and facilitates sepsis-induced immunosuppression resulting from monocyte inability to recognize CX3CL1 and kill pathogenic microorganisms." (PMID 28096568, 2016). "It has been hypothesized that quercetin and kaempferol, the core components of Sini Decoction, may modulate HMOX1 expression (a co-expressed gene in Sini Decoction) through associated signaling pathways to target CX3CR1 (a key gene influencing sepsis prognosis) in patients." (PMID 39495969, 2024). "The expression of CX3CR1 is regulated by the gut microbiota and is correlated with the prognosis of sepsis in patients." (PMID 41532069, 2026). "This study aims to explore the role of gut microbiota components in regulating CX3CR1 expression and its impact on pneumonia-induced lung injury during sepsis." (PMID 41532069, 2026). "A previous microarray study observed a severe down-regulation of CX3CR1 expression on circulating monocytes from septic shock patients and was suggested to be a feature of sepsis-induced immunosuppression." (PMID 39847265, 2025). "The involvement of CX3CL1/CX3CR1 axis in sepsis, therefore, has been reported conflictingly and requires further investigation." (PMID 40508161, 2025).